RNU6-663P (RNA, U6 small nuclear 663, pseudogene)
Gene: Small nuclear RNA gene on chromosome 8 (32,911,493 to 32,911,598, reverse strand). Ensembl gene ENSG00000212407.
Homologues: Orthologues: chimpanzee U6 (97% identical), macaque U6 (94% identical), mouse Gm26122 (60% identical), rat LOC120094865 (58% identical). Paralogues in human: RNU6-536P (78% identical), RNU6-1060P (77% identical), RNU6-522P (77% identical), RNU6-918P (77% identical), RNU6-116P (76% identical), RNU6-1152P (75% identical), RNU6-1201P (75% identical), RNU6-672P (75% identical), RNU6-132P (75% identical), RNU6-196P (75% identical), RNU6-200P (75% identical), RNU6-460P (75% identical), and 1283 more.